INS (insulin)
Diseases named in the same sentence as INS in open-access papers (continued):
Sharing a sentence is not in itself a finding about the gene and the disease.
Hyperglycemia (continued). "We suggest that hyperglycemia may initiate a “feed forward” sequence of elevated BCL11A expression leading to impaired insulin secretion and worsening hyperglycemia, like that seen in T2D patients." (PMID 30242153, 2018). "Our study showed that LM50 provides better control over post-breakfast and post-dinner blood glucose and postprandial glycemic excursions in T2DM patients with mild to moderate hyperglycemia who are receiving premixed human insulin, and thus improves the quality of blood glucose control." (PMID 29520742, 2018). "In an experiment with obese rats, calcium supplementation decreased the production of inflammatory cytokines, oxidative stress, and lipid accumulation in fat cells; such reductions may lead to improved insulin sensitivity and a reduction in DM hyperglycemia." (PMID 29652940, 2018). "Using metabolic analyses such as IVGTTs, MTTs, and insulin assays, as well as immunohistochemistry to determine pancreatic beta cell damage, we show that alloxan treatment induced a diabetic state, as defined as fasting hyperglycemia and hypoinsulinemia." (PMID 29523165, 2018). "As insulin is the first treatment of choice for diabetic patients with uncontrolled hyperglycemia, further studies are needed to determine whether insulin acts synergistically with TubA or counteracts the advantages elicited by TubA in the diabetic heart." (PMID 30046381, 2018). "In this review, we discuss some key pathophysiologies of GDM that may lead to cognitive impairment, specifically hyperglycemia, insulin resistance, oxidative stress, and neuroinflammation." (PMID 30563117, 2018). "Variations in hyperglycemia and insulin use by surgical specialty require further investigation." (PMID 29255628, 2018). "Altered endothelial permeability and reduced blood flow may augment insulin resistance, resulting in exacerbating hyperglycemia, leading to a vicious cycle of reduced blood flow and insulin resistance." (PMID 29414858, 2018). "Furthermore, antenatal exposure to betamethasone results in coexistence of various metabolic disorders in adult offspring, including hyperglycemia, glucose intolerance, low insulin secretory capacity and hyperlipidemia." (PMID 30212527, 2018). "Glucagon release is inhibited by hyperglycaemia, insulin, GLP-1 and somatostatin." (PMID 29412829, 2018). "Typical phenotypes of growth retardation, persistent hyperglycemia, decreased number of insulin-producing β cells, increased number of glucagon-producing α cells, and diabetic complications including diabetic nephropathy, hepatopathy, myopathy and cardiomyopathy were identified in this rabbit model." (PMID 29950431, 2018). "Thus, and in agreement with previous studies, we have found that miR-29a/b1−/− mice exhibit hyperglycemia and reduced insulin concentration, two common features of diabetic patients." (PMID 30346946, 2018). "This improvement could be attributed to the hypoglycemic effects of Trop since hyperglycemia per se induces β-cell death and impairs insulin secretion." (PMID 35539384, 2018). "Hyperglycemia and use of insulin varied by surgical specialty." (PMID 29255628, 2018). "Taken together, our present study demonstrated that attenuated responses to insulin might cumulatively affect glucose metabolism and lead to hyperglycemia in ArKO mice." (PMID 30211334, 2018). "Curiously, in a streptozotocin (STZ)-induced diabetic rat model and insulinopenic model, resveratrol could also reduce hyperglycemia and improve the insulin secretion respectively." (PMID 30273360, 2018). "Feeding HFD to male C57BL/6 mice for 10 weeks resulted in significant rise in body weight (2 fold increase), blood glucose (hyperglycemia), and insulin (hyperinsulinemia) compared to the lean control group, and also the HFD feeding resulted in impaired oral glucose tolerance." (PMID 30524684, 2018).
Hyperglycemia (continued). "In this case, modulation of the neural signalling pathways could increase the effect of exogenous insulin in lowering blood glucose and we would be able to reduce post-prandial glucose excursions, therefore reducing hyperglycemia." (PMID 32232085, 2018). "Moreover, the Japanese population has a higher prevalence of postprandial hyperglycemia than the Caucasian population, which is mostly due to diminished first-phase insulin secretion." (PMID 30441841, 2018). "However, the effect of insulin is repressed in insulin-resistant individuals, and persistent hepatic glucose output contributes to post-prandial hyperglycemia, which is a critical characteristic of metabolic diseases." (PMID 30692925, 2018). "Thus, depletionsin β-cells lead to decreased insulin secretion andconcentration in the body, hyperglycemia, andhyperlipidemia." (PMID 29105385, 2018). "Insulin demand is increased by GCs, and when the compensative insulin secretion is inadequate or compromised, fasting and/or postprandial hyperglycaemia may occur." (PMID 30123187, 2018). "The reason might be due to the decreased level of high glycemic index foods, the total amount of foods rich in carbohydrates, and the increased intake of nuts, which could help improve hyperglycemia and insulin sensitivity." (PMID 29882884, 2018). "However, we determined that the insulin-loaded PAM-PAspPBA-b-PEG has a similar effect to pure insulin in a hyperglycemic state, which indirectly indicates that insulin-loaded PAM-PAspPBA-b-PEG has similar release to pure insulin in the case of hyperglycemia." (PMID 30423891, 2018). "However, d-serine supplementation blunted first and second phase insulin secretion in CD fed animals resulting in hyperglycemia." (PMID 30093356, 2018). "We are currently recruiting in a birth cohort study, titled as “Maternal Antecedents of Adiposity and Studying the Transgenerational role of Hyperglycemia and Insulin” (MAASTHI) in a public hospital; with the aim of assessing maternal glycemic levels on the risk of adverse fetal outcomes." (PMID 30208868, 2018). "Although not statistically significant, the odds of receiving basal-bolus insulin therapy decreased by 2015, which may explain why the frequency of hyperglycemia was higher that year compared to 2012 as detected in the regression analysis." (PMID 29255628, 2018). "However, in the majority of cases, pancreatic β-cells fail to compensate for a chronic fuel surfeit, leading to eventual insulin resistance, hyperglycemia, and an increased supply of glucose to the growing fetus." (PMID 30373146, 2018). "However, in the setting of our study in patients with overt T2D, these dietary factors also reduce hyperglycemia, but fail to affect insulin secretion." (PMID 30619502, 2018). "Insulin was administered for 24 hours, during total parenteral nutrition, at a dosage to maintain a moderate hyperglycemia in CIT, and normoglycemic blood glucose levels in IIT (9.3±0.5 vs 6.5±0.3 mmol/L respectively, P<0.001; coefficient of variation, 9.7±1.4 and 10.5±1.1%, P = 0.43)." (PMID 29300728, 2018). "In addition, isoprenaline (a β-adrenergic receptors agonist) shows hyperglycemia and provokes a considerable elevation of insulin, and propranolol (a β-adrenergic receptor antagonist) partially and temporarily inhibits the secretion of insulin." (PMID 30460079, 2017). "Impairment of insulin actions is known as insulin resistance, the failure which is located at the signaling pathways held after insulin binding to its receptor.Chronic occurrence of the mentioned failure leads to hyperglycemia (Fernández-Mejía 2013)." (PMID 28367665, 2017). "Hyperglycemia or blockade of insulin signaling reduces the expression of ORAI1-3." (PMID 29203863, 2017). "Nevertheless, in patients treated with basal insulin and in cases where the glycemic profile shows a clear predominance of prandial hyperglycemia, a drug with a more specific action against this abnormality could prove useful." (PMID 28115994, 2017).
Hyperglycemia (continued). "Furthermore, the insulin concentrations in the plasma are inadequate to compensate for hyperglycemia." (PMID 28974008, 2017). "Increased plasma glucagon and beta hydroxybutyrate levels as well as a number of characteristic metabolomic changes characterized the 2-year-old MIDY pig with limited insulin treatment as a clinically relevant model of chronic insulin insufficiency and hyperglycemia." (PMID 28752056, 2017). "CB0313.1 modulates gut microbiota composition to selectively enrich butyrate-producing bacteria, promote GLP-1 and insulin secretion, activate the GLP-1/insulin/pIRS1-pAKT-PPARγ-G6Pase/Pck1 pathway, and reduce hepatic glucose output, which ultimately mitigates hyperglycemia in diabetic host mice." (PMID 28765642, 2017). "Here, EEMn reduced hyperglycemia and spared adipose and skeletal muscle mass, which could explain, at least in part, insulin effect." (PMID 28567440, 2017). "Interestingly, bioactive constituents which simultaneously inhibit α-glucosidase and PTP1B enzymes display synergistic effect to antagonize hyperglycaemia and hence significantly improve insulin sensitization." (PMID 28933230, 2017). "Interestingly, these findings are consistent with lifestyle intervention, whereby patients with chronic hyperglycaemia have blunted gains in aerobic fitness 41 as well as insulin sensitivity and fat oxidation." (PMID 28706732, 2017). "Very high maternal hyperglycemia could result in fetal insulin hypersecretion, and ultimately, an overweight newborn, as was the case in two of our patients." (PMID 28663157, 2017). "One hour after insulin therapy, the blood glucose of the animals was reduced to approximately half the original values, and 2 h after treatment, it increased again, as the animals displayed hyperglycemia." (PMID 28649241, 2017). "Given that she was having frequent hypoglycemic episodes, mainly in the evening and during the night, she had actually stopped her prandial insulin and was only using the rapid-acting insulin for hyperglycemia if the plasma glucose concentration was ≥300 mg/dL." (PMID 28748191, 2017). "Taken together the findings point to a vicious cycle in which elevated nutrients, partly via Yy1, decrease Sox5 expression and lead to impaired insulin secretion, which in turn may aggravate the hyperglycemia." (PMID 28585545, 2017). "In addition, these cells secrete human insulin into the serum of mice after transplantation in a glucose-regulated manner, and transplantation of these cells improves hyperglycemia in diabetic mice." (PMID 28758131, 2017). "However, hyperglycemia was further exacerbated by Rapamycin treatment in ZO rats and this is consistent with suppression of insulin." (PMID 28408970, 2017). "Notably, a simple intervention such as STS, as well as insulin, prevented the hyperglycemia induced by Dexa or Rapa and reversed the sensitization effects in mice." (PMID 28358805, 2017). "Interestingly, atorvastatin plus insulin (combined) treatment led to amelioration of the inflammation and destruction of pancreatic cells leading to an increase in insulin secretion which subsequently improved conditions of hyperglycemia." (PMID 29051569, 2017). "Notably, STS was more potent in preventing this hyperglycemia-induced sensitization than insulin treatment alone (p-value < 0.0001), indicating that fasting has a broader effect that is partly independent of glucose." (PMID 28358805, 2017). "According to in vivo studies in diabetic hyperinsulinemic mice showing that TGZ has potent glucose and insulin-reducing effects, several reports have demonstrated that both TGZ and PIO reduce hyperglycemia, hyperinsulinemia, and hypertriglyceridemia and improve insulin sensitivity in T2DM patients." (PMID 28275367, 2017).
Hyperglycemia (continued). "Destruction of insulin producing β-cells is one of the serious chronic autoimmune disorders, characterized by infiltrating autoreactive lymphocytes, macrophages and other immune cells leading to diminished insulin secretion and hyperglycemia." (PMID 28878669, 2017). "If hyperglycemia persists, it should be managed by reducing excess glucose intake, since higher insulin might hamper increased glucose oxidation in this period." (PMID 29035319, 2017). "It is activated dependently and independently of insulin during long lasting hyperglycemia, requiring generation of glucose-6-phoshate by the glucokinase and binds to the carbohydrate responsive element (ChoRE) in the promoter region of the pyruvate kinase (liver type)." (PMID 29262643, 2017). "It remains still unclear, however, whether hyperglycemia also annihilates the benefits of insulin pre-conditioning." (PMID 28376800, 2017). "Studies have also shown that low levels of PA are predominantly associated with metabolic defects related to IGT (systemic insulin resistance and 2-hour hyperglycemia) as compared with i-IFG (defective first-phase insulin secretion, decreased basal hepatic glucose uptake, and fasting hyperglycemia)." (PMID 28973497, 2017). "This supported the general concept regarding the role of glucagon in contributing to hyperglycemia but also indicated that there may be a minimal insulin requirement for glucagon antagonism to be effective." (PMID 28323959, 2017). "BACKGROUND: The primary purpose of this study is to determine whether insulin detemir is equivalent to insulin glargine in controlling hyperglycemia for the adult hospitalized patient on a basal-bolus treatment regimen." (PMID 28970434, 2017). "T2DM occurs when an already insulin-resistant individual develops beta cell dysfunction and is therefore unable to produce the necessary amount of insulin that is required to maintain normoglycaemia, and as a result hyperglycaemia predominates." (PMID 29146657, 2017). "No previous studies have been conducted to examine whether CLW improves hyperglycemia by improving insulin sensitivity and secretion." (PMID 29104217, 2017). "However, they are insulin resistant, exhibit elevated levels of circulating insulin and develop hyperglycemia with advancing age." (PMID 28670222, 2017). "High insulin and hyperglycemia are prominent in this model by 10–14 weeks of age." (PMID 28640904, 2017). "In critically ill patients with permissive hyperglycemia, it is uncertain whether exogenous insulin administration suppresses or enhances c-peptide secretion (a marker of pancreatic beta-cell response)." (PMID 28497374, 2017). "Without adequate treatment, prolonged hyperglycemia can cause glucose toxicity that can progressively impair insulin secretion." (PMID 28167928, 2017). "Furthermore, the LADA patients undergoing insulin treatment perceived a greater frequency of hyperglycemia than the other diabetic groups." (PMID 29062603, 2017). "Because we did not include a group of animals treated with a specific Akt inhibitor nor studied other pathways including the hexosamine or Akt-mTOR system the exact of role of Akt as a mediator of insulin-pre-conditioning and hyperglycemia remains to be determined." (PMID 28376800, 2017). "This concept is supported by a prospective randomised study, which concluded that once daily subcutaneous insulin glargine administered during intravenous insulin infusions, safely prevented rebound hyperglycaemia without risk of hypoglycaemia." (PMID 28659865, 2017). "In a post-hoc NMA analysis, based on an indirect comparison, the odds of progressing to insulin therapy to manage hyperglycemia during pregnancy was greater for a LGI diet than to a combined LGI and high-fibre diet (odds ratio [OR] = 5.92 [95% CrI: 1.20, 36.41])." (PMID 28771519, 2017).
Hyperglycemia (continued). "The study was designed to test the hypothesis that acute hyperglycemia diminishes the cardioprotective effects following a 20-min pre-ischemic pre-conditioning with insulin in the isolated rat heart using the Langendorff system." (PMID 28376800, 2017). "This insufficient insulin secretion leads to chronic hyperglycemia and T1D." (PMID 29033899, 2017). "However, failure in insulin secretion or disturbance in insulin sensitivity give rise to uncontrolled blood glucose levels (hyperglycemia) and ultimately results in DM." (PMID 29209017, 2017). "We speculate that a small elevation of plasma glucose induces a vicious cycle of impaired insulin secretion and hyperglycemia." (PMID 28954230, 2017). "Chronic hyperglycaemia results in reduced insulin sensitivity and reduced β-cell function." (PMID 28231831, 2017). "The study authors’ objective was to determine whether insulin detemir and insulin glargine were similar if used in two similar size and type hospitals in controlling hyperglycemia in the adult hospitalized patients on basal-bolus treatment regimens." (PMID 28970434, 2017). "Conversely, animals injected with higher STZ doses (≥50 mg/kg IP or IV) exhibit overt hyperglycemia, complete absence of insulin, weight loss and as such are prone to a high mortality rate." (PMID 29075006, 2017). "However, β cell apoptosis caused by high-glucose toxicity results in decreased β cell function and insulin sensitivity, further reducing insulin secretion in diabetic patients with long-term hyperglycemia." (PMID 28394923, 2017). "In animal experiments, glucose homeostasis in diabetic rats, normalization of hyperglycemia in diabetic mice and insulin sensitization effect in Type2 diabetes patients are few examples from numerous reports on anti-diabetic effects of various vanadium compounds." (PMID 28072841, 2017). "Risk factors of persistent hyperglycemia at 6–12 weeks after GDM pregnancy were inclusive of FPG ≥ 100 at the time of OGTT in pregnancy, earlier diagnosis of GDM in pregnancy, systolic blood pressure, and the need for insulin inject or metformin therapy." (PMID 28491872, 2017). "Moreover, our study demonstrated that intensive insulin therapy resulted in an increase of fibrinolysis process, which is of great benefit for patients with hyperglycemia with ACS." (PMID 29138181, 2017). "Our results indicate that ERV1tg may respond promptly to transient hyperglycemia through increased insulin secretion." (PMID 28993702, 2017). "Although we are unaware of any direct evidence for improved beta-cell function with carbohydrate-restriction in individuals with T2D, associative evidence supports that providing beta-cell rest by removing hyperglycemia can reverse the insulin secretory defects present in animal models of T2D." (PMID 29075629, 2017). "Hyperglycemia was identified in six animals (12%), two of which were insulin-dependent diabetics." (PMID 29069262, 2017). "The 2hPG identifies patients who are nearly or completely insulin resistant, a condition where the liver and muscles require more insulin to suppress the hepatic glucose production and glucose uptake, respectively, that results in postprandial hyperglycemia." (PMID 28854264, 2017). "Furthermore, the reduction of dobutamine-induced insulin level by PTX appears to be due to inhibiting effect of PTX-against dobutamine-induced hyperglycemia." (PMID 30460079, 2017). "Although it was previously shown that restoring normal insulin levels could improve bone quality in T1DM patients, early intervention is needed to prevent detrimental “metabolic memory” caused by hyperglycemia." (PMID 28283030, 2017). "However, an extremely high prevalence of hyperglycaemia requiring insulin treatment was seen in the high-dose corticosteroid group (5.0% [no-corticosteroid] vs 21.7% [high-dose corticosteroid], p = 0.0002)." (PMID 29284447, 2017).